GPX4 (glutathione peroxidase 4)
Diseases named in the same sentence as GPX4 in open-access papers (continued):
Sharing a sentence is not in itself a finding about the gene and the disease.
renal fibrosis (continued). "Thus, in this study, we aimed to uncover the mechanistic link between TGF-β/Smad3 signaling and GPX4-dependent ferroptosis in the development of renal fibrosis." (PMID 41079940, 2025). "Finally, we explored the potential role of GPX4 in Smad3-driving renal fibrosis by specifically silencing GPX4 in the UUO kidney of Smad3-KO mice and Smad3-KO mouse embryo fibroblasts (MEFs)." (PMID 41079940, 2025). "In addition, further researches are still needed to determine the exact mechanism of SIRT1 on GPX4 in renal fibrosis." (PMID 39872048, 2024). "Taken together, our data suggested that DSI protected renal fibrosis against ferroptosis may be partially via SIRT1/GPX4 activation, highlighting that the potential effects of DSI as a novel therapeutic drug for limiting renal fibrosis." (PMID 39872048, 2024). "Taken together, our results indicated that DSI could protect against ferroptosis to attenuate renal fibrosis by activating the SIRT1/GPX4 pathway." (PMID 39872048, 2024). "Second, various strategies may be useful to assess the direct relationship between ferroptosis and renal fibrosis in the future, including the use of GPX4 knockout animals and GPX4 knockout cells." (PMID 34511597, 2021). "Thus, it is possible that targeting the Smad3/GPX4-ferroptosis regulatory pathway may be a promising therapeutic strategy for treatment of renal fibrosis." (PMID 41079940, 2025). "Importantly, we also found that GPX4 was a downstream target gene of Smad3 and functioned to protect against Smad3-mediated renal fibrosis as silencing GPX4 restored UUO-induced severe renal fibrosis in Smad3 KO mice and in TGF-β1-stimulated Smad3 KO MEFs and SIS3-treated HK-2 cells." (PMID 41079940, 2025). "Ferroptosis was clearly evident in IR-induced renal fibrosis but was substantially ameliorated in HDAC4-KO mice, as indicated by decreased ACSL4 expression and restored GPX4 levels." (PMID 41282137, 2025). "Both compounds ameliorated renal fibrosis and suppressed ferroptosis by downregulation Fe2+, TFR1, and ROS levels, while concurrently upregulating the decreased levels of SLC7A11 and GPX4." (PMID 40766752, 2025). "This was demonstrated by the findings that silencing GPX4 restored high levels of 4-HNE, TFR1 and the severity of renal fibrosis in the UUO kidney of Smad3 KO mice and TGF-β1-treated Smad3 KO MEFs and HK-2 cells treated with SIS3." (PMID 41079940, 2025). "In total, these findings suggested that the reduction of renal fibrosis by DSI treatment may be due to the activation of SIRT1 and GPX4." (PMID 39872048, 2024). "After the intervention of SAL, renal fibrosis and ferroptosis in 8-month-old SAMP8 mice can be alleviated, which may be related to regulating renal iron metabolism, reducing iron deposition, regulating SLC7A11 and GPX4 protein expression, and finally alleviating renal ferroptosis." (PMID 36432138, 2022).
retinal degeneration (9 papers, 2013 to 2025). Degeneration of the retina. "Specific knockout of GPX4 in the RPE of mice results in oxidative stress-mediated retinal degeneration." (PMID 39984833, 2025). "Collectively, these findings indicate that GPX4 overexpression markedly attenuates oxidative stress-driven retinal degeneration and preserves photoreceptor outer-segment architecture." (PMID 41394869, 2025). "In multiple oxidative stress models of retinal degeneration, elevated GPX4 expression has been shown to protect photoreceptors and RPECs, suggesting that increasing GPX4 expression may represent a potential gene therapy approach for patients with AMD." (PMID 41394869, 2025). "In RP, overexpression of a key ferroptosis factor (Gpx4) and application of ferroptosis inhibitors could work against retinal degeneration and promote cone photoreceptor survival." (PMID 39519580, 2024). "Possibly, there may another GPX family protein or GPX4-independent systems responsible for the inhibition of ferroptosis in retinal cells during retinal degeneration." (PMID 36396940, 2022). "The up-regulation of Gpx4 protected retinal structure and function in paraquat, H2O2 or hyperoxia models of oxidative-damage-induced retinal degeneration in transgenic mice with inducible expression of Gpx4 in photoreceptors." (PMID 24057278, 2013). "Therefore, the upregulation of the SLC7A11/GSH/GPX4 axis in RPE cells may be one of the PEDF‐mediated antioxidant mechanisms to counteract the pathogenesis of oxidative stress‐induced RPE damage and retinal degeneration." (PMID 40703032, 2025).
Anxiety (8 papers, 2020 to 2025). Intense feelings of nervousness, tension, or panic often arise in response to interpersonal stresses. "Current studies indicated that EDA attenuated CSDS-evoked depressive symptoms and CSDS-induced anxiety behaviors, and the underlying mechanisms were associated with the alteration of expression of Sirt1/Nrf2/HO-1/Gpx4 pathway in the Hip." (PMID 35130906, 2022). "Furthermore, GPX4 could prevent neuronal dysfunction and PD-like symptoms, and GPX4 loss in dopaminergic neurons induced anxiety behavior and diminished spontaneous locomotor activity." (PMID 33204324, 2020). "Accordingly, we hypothesized that EDA might ameliorate depressive and anxiety-like behaviors via Sirt1/Nrf2/HO-1/Gpx4 pathway." (PMID 35130906, 2022). "Therefore, we speculated that EDA improved depressive and anxiety-like behaviors by activating the Sirt1/Nrf2/HO-1/Gpx4 signaling pathway." (PMID 35130906, 2022). "Then, we found the proteins expression of GPX4, SLC7A11, FTH, ACSL4 and FPN, which were also significantly reduced in depressive and anxiety-like behavioral mice whose symptoms were induced by alcohol." (PMID 36430312, 2022). "In addition, Gpx4 knockdown in CSDS mice abolished EDA-generated efficacy on depressive and anxiety-like behaviors." (PMID 35130906, 2022).
preeclampsia (8 papers, 2016 to 2025). Preeclampsia is a hypertensive disorder of pregnancy that is characterized by new-onset hypertension with proteinuria presenting after 20 weeks of gestation, and depending on mild or severe forms may initially present with severe headache, visual disturbances, and hyperreflexia. "An increased expression of ACSL-4 and ALOX-5 together with decreased GPX4 levels in the placenta has been associated with trophoblastic ferroptosis and different obstetric complications such as preeclampsia." (PMID 38790696, 2024). "The GPX4 SNP rs4807542 was reported to be associated with Kashin–Beck disease, biliary tract cancer, and preeclampsia in a Chinese Han population." (PMID 33770380, 2022). "In a murine model of preeclampsia, puerarin administration attenuated placental injury and was found to activate key antiferroptotic pathways, including the upregulation of glutathione peroxidase 4 (GPX4) and the cystine/glutamate antiporter (SLC7A11)." (PMID 41020807, 2025). "GPX4 was observed to significantly decrease in preeclampsia samples whereas the expression of GPX4 had been used as an important marker for ferroptosis." (PMID 35888713, 2022). "DJ-1 can mediate the trophoblast cells ferroptosis and play a protective role in the pathogenesis of preeclampsia by regulating the Nrf2/GPX4 signaling pathway." (PMID 35190654, 2022). "GPx4 also plays important role in preeclampsia in women, because decreased expression of this enzyme may lead to preeclampsia development." (PMID 34068371, 2021).
autoimmune disease (7 papers, 2022 to 2026). A disorder resulting from loss of function or tissue destruction of an organ or multiple organs, arising from humoral or cellular immune responses of the individual to their own tissue constituents. "Current markers (e.g., GPX4 expression, serum iron, and lipid peroxides) lack specificity for LN, as they are altered in other autoimmune diseases or kidney disorders." (PMID 41425591, 2025). "Collectively, these conditional GPX4 depletion models suggest a broad regulatory role for GPX4 in the prevention of inflammatory and autoimmune diseases." (PMID 38515187, 2024). "Se deficiency is associated with autoimmune diseases (AID) and may trigger disease onset directly by increasing ferroptosis rate of neutrophils due to insufficient expression of glutathione peroxidase 4 (GPx4)." (PMID 35139480, 2022). "These compounds effectively intervene in the overactive inflammation and immune responses characteristic of rheumatic and autoimmune diseases by modulating various signaling pathways, including the TNF, Toll-like, IL-6, RANKL, MAPK, PI3K/AKT/mTOR, JAK/STAT, and NRF2/GPX4 pathways." (PMID 39524446, 2024).
breast tumor (7 papers, 2021 to 2024). "Immunohistochemical staining for the ferroptosis marker GPX4 in breast tumour tissues indicated a significant (p < 0.05) downregulation of GPX4 in the ORes treatment group." (PMID 39881871, 2024). "Compared with normal breast tissue, the expression of xCT components SLC7A11 and SLC3A2 is increased in a subset of patient breast tumor tissues, and their co-expression is closely related to the expression of GPX4." (PMID 35057861, 2022). "The results revealed that pretreatment with Res enhanced the expression of GPX4 protein in breast tumor cells by NK cells, indicating that Res-pretreated NK cells can increase the sensitivity of breast tumor cells to ferroptosis, thus enhancing the anti-tumor activity of NK cells." (PMID 38891683, 2024). "For instance, DMOCPTL (a derivative of natural product parthenolide) binds to glutathione peroxidase 4 (GPX4), upregulating early growth response 1 (EGR1) and inducing mitochondrial-mediated apoptosis, effectively inhibiting breast tumor growth." (PMID 39664391, 2024).
cardiac hypertrophy (7 papers, 2021 to 2026). "To investigate the activation of ferroptosis in cardiac hypertrophy, we analysed several ferroptosis‐associated markers, including malondialdehyde (MDA), prostaglandin‐endoperoxide synthase 2 (Ptgs2), Gpx4, and mitochondrial morphology." (PMID 40000392, 2025). "Moreover, TQ inhibits cardiomyocyte ferroptosis and apoptosis by downregulating PTGS2, Bax, and upregulating GPX4, Bcl-2, thereby alleviating cardiac hypertrophy and dysfunction." (PMID 41614426, 2026). "Cardiac hypertrophy in response to triiodothyronine or isoproterenol treatment was found to upregulate the expression of MsrB1, GPX3, GPx4, and Txnrd1, leading to the speculation that their increased expression may mitigate cardiac damage following induction of hypertrophy." (PMID 34579115, 2021). "The results revealed that fisetin treatment could markedly abate DOX-induced cardiotoxicity by alleviating cardiac dysfunction, ameliorating myocardial fibrosis, mitigating cardiac hypertrophy in rats, and attenuating ferroptosis of cardiomyocytes by reversing the decline in the GPX4 level." (PMID 35273493, 2021). "When the FSP1 and/or GPX4 pathways were blocked, compared to when DHODH was not inhibited, inhibiting DHODH aggravated myocardial hypertrophy and myocardial fibrosis." (PMID 39737072, 2024).
head and neck squamous cell carcinoma (7 papers, 2020 to 2025). A squamous cell carcinoma that arises from any of the following anatomic sites: lip and oral cavity, nasal cavity, paranasal sinuses, pharynx, larynx, and salivary glands. "Dihydroartemisinin (DHA) is a derivative and active metabolite of artemisinin, decreasing the levels of glutathione peroxidase 4 (GPX4) in head and neck squamous cell carcinoma (HNSCC) cells." (PMID 32516941, 2020). "Radiosensitive head and neck squamous cell carcinoma (HNSCC) cells downregulate GPX4 expression upon ionizing radiation (IR) exposure, inducing ferroptosis, whereas radioresistant HNSCC cells fail to do so." (PMID 39297393, 2025). "Importantly, GPX4 expression was positively correlated with the expression levels of monocyte markers (CD14 and CD115) and M2 macrophage markers (VSIG4 and MS4A4A) both in ESCA and in head and neck squamous cell carcinoma (HNSC)." (PMID 34722530, 2021).
hematoma (7 papers, 2021 to 2025). A hematoma is a collection of blood from a vascular structure into an extravascular space. "Our results demonstrated that DDT reduced hematoma volume, decreased iron deposition, lowered malondialdehyde (MDA) levels, and upregulated glutathione peroxidase (GPX4) and SLC7A11 expression in affected brain regions." (PMID 39525631, 2024). "The present study provides a feasible candidate of DPX suppressing ferroptosis to reduce WMI through increasing the expression of GPX4 and FSP1 around hematoma in mice after ICH." (PMID 35965685, 2022). "To investigate the antiferroptosis activity of PIH after ICH, we examined the intracellular iron levels, MDA levels, ROS production, and GPX4 and cyclooxygenase-2 (COX-2) expression in ferroptotic neurons within hematoma-adjacent brain tissue." (PMID 34541001, 2021). "Additionally, the levels of GPX4 and SLC7A11 in the brain tissue around the hematoma were significantly reduced, while the levels of ACSL4 and COX-2 were significantly increased (P < 0.001)." (PMID 39601768, 2025). "In conclusion, the present study provides a rationale that ferroptosis plays a significant role in WMI resulting from iron and ROS accumulation around hematoma, and DPX decreases iron and ROS accumulation to suppress ferroptosis through upregulating of GPX4 and FSP1." (PMID 35965685, 2022).
iron overload (7 papers, 2022 to 2026). "Here, we further revealed that the causative factor for AMT occurrence was iron overload due to high GPX4 expression." (PMID 40860189, 2025). "Therapeutically, the review will consider targeting these nodes with GPX4 inhibitors or iron overload, synergized with immunotherapy for immunogenic cell death." (PMID 41096949, 2025). "First, Ferroptosis is characterized by iron overload, the accumulation of reactive oxygen species, and a reduction in GPX4 levels." (PMID 41278282, 2025). "Iron overload, GPX4/GSH, and lipid peroxidation are the main mechanisms leading to the steady state imbalance of iron overload." (PMID 35844870, 2022).
parasitic infections (7 papers, 2021 to 2025). "Both Ag-specific CD8+ and CD4+ T cells deficient for glutathione peroxidase 4 (Gpx4) are unable to expand or protect against viral and parasitic infection." (PMID 34899706, 2021). "GPX4 plays a role in primary T cell responses to viral and parasitic infections by protecting T cells from ferroptosis and supporting T cell expansion." (PMID 36017103, 2022). "In particular, T cells lacking GPX4 failed to expand and to protect mice from acute viral and parasite infections." (PMID 40760119, 2025). "Indeed, early studies on the role of GPX4 on T cell activity established that GPX4 is critical to antigen-specific CD4 T and CD8 T cells by functioning to, not only prevent T cell-ferroptosis but to also, confer effective protection against viral and parasitic infections." (PMID 35065965, 2022). "Moreover, it has been shown that in the absence of GPX4, T cells undergo apoptosis due to enhanced lipid peroxidation, and GPX4 seems to be essential to protect T cells against viral and parasitic infections, further stretching the importance of this pathway for T cell function and persistence." (PMID 36139021, 2022).
Sedaghatian-type spondylometaphyseal dysplasia (7 papers, 2019 to 2025). "The aim of this study was to examine, in biochemical detail, the functional role of the Arg152 residue in the selenoprotein Glutathione Peroxidase 4 (GPX4), whose mutation to His is involved in Sedaghatian-type Spondylometaphyseal Dysplasia (SSMD)." (PMID 37413766, 2023). "GPX4 gene mutations were also responsible for a rare pediatric syndrome (the Sedaghatian-type spondylometaphyseal dysplasia, OMIM #250220) characterized by severe neurological defects, seizures, and cerebellar hypoplasia." (PMID 34439515, 2021). "In humans, loss-of-function mutations (i.e., frameshift or nonsense) in the GPX4 gene are associated with the manifestation of Spondylometaphyseal dysplasia Sedaghatian type (SMDS)." (PMID 33665191, 2021). "The ultrarare pediatric syndrome Sedaghatian-type spondylometaphyseal dysplasia (OMIM #250220) results from mutations in the GPX4 gene." (PMID 30921410, 2019). "Sedaghatian-type spondylometaphyseal dysplasia (OMIM #250220) is an ultrarare pediatric disorder caused by mutations in the GPX4 gene characterized by seizures and cerebellar hypoplasia." (PMID 30921410, 2019). "Thus, mutations of the GPX4 gene are responsible for Sedaghatian-type spondylometaphyseal dysplasia (OMIM #250220), a rare pediatric syndrome characterized by severe neurological defects, seizures, and cerebellar hypoplasia." (PMID 37396923, 2023).
amyotrophic lateral sclerosis (6 papers, 2023 to 2026). Amyotrophic lateral sclerosis (ALS) is a neurodegenerative disease characterized by progressive muscular paralysis reflecting degeneration of motor neurons in the primary motor cortex, corticospinal tracts, brainstem and spinal cord. "At the genetic level, depletion of Gpx4 promotes neuronal damage and neurodegeneration in mice, while Gpx4 overexpression prolongs survival and delays disease onset in amyotrophic lateral sclerosis models." (PMID 38844964, 2024). "As the critical regulator, glutathione peroxidase 4 (GPX4) has been demonstrated to be down-regulated in amyotrophic lateral sclerosis (ALS)." (PMID 36443440, 2023). "A group observed that in a mouse model of ferroptosis with GPX4 neuronal inducible knockout, the ablation of GPX4 in neurons resulted in a rapid paralysis and severe muscle atrophy, which are features of amyotrophic lateral sclerosis." (PMID 37259454, 2023). "In the case of amyotrophic lateral sclerosis, a relationship was found between disease progression and glutathione peroxidase 4 (GPX4) levels, an enzyme belonging to the antioxidant system, which is responsible for preventing the formation of lipid peroxides." (PMID 37259454, 2023).
Arthritis (6 papers, 2024 to 2026). Inflammation of a joint. "Arthritis histopathological scores indicated that both Fer‐1 and GPX4 overexpression significantly reduced the severity of TMJOA and effectively prevented the loss of chondrocytes." (PMID 38686488, 2024). "AB4 treatment inhibits spinal GSK‐3β activity, enhances Nrf2/GPX4 antioxidant response, reduces Drp1‐mediated mitochondrial ROS production, suppresses NLRP3 inflammasome activation and alleviates arthritis pain." (PMID 38334255, 2024). "Additionally, crosstalk between β‐glu‐Mφ and CIA‐FLS protects arthritis synovial FLS from ferroptosis via FSP1/CoQ10 axis, not the GSH/GPX4 pathway." (PMID 41255239, 2025).